POTEI (POTE ankyrin domain family member I)
Synonyms: POTE2beta
Tractability: PROTAC: ubiquitination databases record sites on it.
Gene: Protein-coding gene on chromosome 2 (130,459,455 to 130,509,707, reverse strand). Ensembl gene ENSG00000196834.
Gene Ontology:
Molecular function: protein kinase binding; structural constituent of postsynaptic actin cytoskeleton
Biological process: axonogenesis; cell motility; postsynaptic actin cytoskeleton organization
Cellular component: extracellular exosome; extracellular region; actin cytoskeleton; actin filament; axon; cytoplasm; membrane; NuA4 histone acetyltransferase complex; synapse
Genetic constraint (gnomAD): Loss-of-function variants: 11 observed, 16.19 expected, observed/expected ratio (o/e) 0.68, 90% interval 0.43 to 1.12. The upper end of that interval is the gene's LOEUF score, 1.12, which puts it in group 4 of 6, group 1 being the genes least tolerant of losing a copy. Missense variants: 195 observed, 294.08 expected, observed/expected ratio (o/e) 0.66, 90% interval 0.59 to 0.75. Synonymous variants: 73 observed, 97.42 expected, observed/expected ratio (o/e) 0.75, 90% interval 0.62 to 0.91.
Homologues: Paralogues in human: POTEE (97% identical), POTEF (97% identical), POTEJ (96% identical), POTEB3 (47% identical), POTED (47% identical), POTEB (44% identical), POTEB2 (44% identical), POTEC (44% identical), POTEH (43% identical), POTEG (43% identical), POTEM (43% identical), POTEA (34% identical), and 2 more.
Diseases named in the same sentence as POTEI in open-access papers:
POTEI is named in the same sentence as 4 diseases in open-access papers, as found by Europe PMC text mining. Sharing a sentence is not in itself a finding about the gene and the disease. The quoted sentences say what the papers report.
Waardenburg syndrome (1 paper, 2022). A disorder characterized by varying degrees of deafness and minor defects in structures arising from neural crest, including pigmentation anomalies of eyes, hair, and skin. "Six new genes were associated with NSHI: INPP4B, CCDC141, MYO19, DNAH11, SOX9, and POTEI; and one new gene, PAX8, was associated with Waardenburg syndrome." (PMID 35440622, 2022).
tumor (1 paper, 2020). "Serum levels of POTE (POTE ankyrin domain family member I), a paralog of POTEI (POTE ankyrin domain family member I), in NSCLC patients are associated with TNM stage (tumor extension, nodal status, and metastatic spread incorporated into the staging system)." (PMID 32536039, 2020).
POTEI also shares sentences with these, for which no sentence is quoted: hearing loss (1 paper); infection (1).